KRAS (KRas proto-oncogene, GTPase)
Diseases named in the same sentence as KRAS in open-access papers (continued):
Sharing a sentence is not in itself a finding about the gene and the disease.
colorectal cancer (continued). "Collectively, our data suggest that KRAS‐ or BRAF‐mutant colorectal cancer lines are likely selectively dependent on Ras‐mediated RAD51‐dependent HRR signaling for survival." (PMID 28173629, 2017). "We target common point mutations in the BRAF, KRAS and PIK3CA oncogenes in archival colorectal cancer samples to precisely map the spatial and morphological context of mutant subclones." (PMID 29222441, 2017). "In a previous study of combined lung cancer, colorectal cancer and melanoma specimens, kinase-impaired BRAF mutants were associated with a higher incidence of a concomitant activating KRAS/NRAS mutation." (PMID 29228562, 2017). "Yun and colleagues reported recently that the oxidised form of AA, dehydroascorbate (DHA) rather than AA was responsible for selectively killing glycolysis-driven colorectal cancer cells with BRAF and KRAS mutations." (PMID 28737676, 2017). "About 40% colorectal cancers (CRCs) contain KRAS or BRAF mutant genes and are resistant to treatments with individual inhibitors of RTKs, AKT, MEK, or BRAF." (PMID 28002807, 2017). "In colorectal cancer, EGFR antibody-resistant subclones with pre-existing KRAS mutations emerged in 38% of patients following 5–6 months of treatment with panitumumab." (PMID 28716075, 2017). "The aim of this study is to analyze the association between KRAS and VEGF gene 3’-UTR SNPs and genetic susceptibility to colorectal cancer (CRC)." (PMID 28328959, 2017). "In a mouse model of KRAS-mutant colorectal cancer, anti-CTLA-4 profoundly increases the extent of T-cell activation and infiltration into tumors, and these effects were found to be only minimally impacted by MEK inhibition." (PMID 28807001, 2017). "KRAS mutations drive resistance to targeted therapies, including EGFR inhibitors in colorectal cancer (CRC)." (PMID 28593995, 2017). "We performed differential expression analysis on 677 samples across 3 colorectal cancer datasets, from which 248 gene probes were identified as being differentially expressed between KRAS-MT and KRAS-WT." (PMID 27965461, 2017). "This validation analysis successfully confirmed that miR-31 and miR-135b were significantly up-regulated, and miR-193a-3p was significantly down-regulated in BRAF-mutant colorectal cancers compared to KRAS/BRAF-wild-type cancers." (PMID 29115941, 2017). "In metastatic/advanced colorectal cancer, a patient’s suitability for treatment with anti-EGFR monoclonal antibodies is determined by the presence of mutations in KRAS and/or NRAS." (PMID 29029407, 2017). "The three data points where the cancer incidence is greater than the linear regression expectation correspond to PIK3CA E545K, KRAS G12D, and KRAS G12V in colorectal cancer, a cancer whose incidence is considered to have an extrinsic exposure component." (PMID 28755461, 2017). "Nucleotide exchanges (GGT → GTC) encoding the G12 V KRAS mutation in AMCPAC01 are rare, but have been previously reported in one pancreatic and one colorectal cancer patients." (PMID 28435405, 2017). "We aimed to evaluate the potential different prognostic values of KRAS exon 2 codons 12 and 13 after lung metastasectomy in colorectal cancer (CRC)." (PMID 27911859, 2017). "We immunohistochemically evaluated EZH2 expression and assessed miR-31 and gene mutations [KRAS (codon 61/146), NRAS (codon 12/13/61), and BRAF (codon 600)] in 109 patients with colorectal cancer harboring KRAS (codon 12/13) wild-type." (PMID 28147317, 2017).
colorectal cancer (continued). "Activating mutations in the KRAS and BRAF genes, leading to hyperactivation of the RAS/RAF/MAPK oncogenic signaling cascade, are common in patients with colorectal cancer (CRC)." (PMID 27999210, 2017). "Among the human colorectal cancer (CRC) cell lines, a cell line with a KRAS mutation on codon 12, the KRASG12V-mutated colon cancer cell line SW480, was chosen." (PMID 28800074, 2017). "We report that the DNA double‐strand break repair (DSB repair) by homologous recombination (HR) pathway was enhanced in KRAS‐mutant colorectal cancer cells through hyperactivation of c‐MYC." (PMID 28173629, 2017). "This also demonstrated that our results from differential analysis provided highly accurate gene signatures for KRAS-MT colorectal cancers." (PMID 27965461, 2017). "Tumor response of patients with KRAS/BRAF-wild-type colorectal cancer who received anti-EGFR therapy based upon the miR-193a-3p expression status." (PMID 29115941, 2017). "We report the importance of upregulated HRR in promoting the survival of KRAS‐mutant colorectal cancer cells." (PMID 28173629, 2017). "Enhanced RAD21 expression was associated with early relapse and poor prognosis of breast cancer and KRAS mutant colorectal cancer." (PMID 28977903, 2017). "Our in-vitro model demonstrates that the NDRG2 overexpression attenuates several aspects of tumorigenesis including the proliferation and invasive potential of human colorectal cancer cell line HCT116, a widely used model for KRAS mutated colorectal cancer." (PMID 29399558, 2017). "The level of mutated cfDNA is prognostic in other cancer types as well, with higher levels of mutated KRAS and BRAF DNA found in colorectal cancer patients with lower survival." (PMID 29137355, 2017). "The G12D, G12R, and G13D KRAS mutations detected in AMCPAC cell lines were reported in various cancers, such as pancreatic carcinoma, non-small cell lung cancer, stomach cancer, colorectal cancer, and leukemia." (PMID 28435405, 2017). "ADAM17 was shown to negatively regulate c-MET signaling by increasing the levels of soluble MET in a KRAS mutant colorectal cancer model." (PMID 29230082, 2017). "Cetuximab and panitumumab, two antibodies against EGFR, can only prolong survival of colorectal cancer patients with normal KRAS." (PMID 28002807, 2017). "Using cross‐species validation from the largest yeast genetic interactome, we provide evidence of the novel role of KRAS signaling biology in upregulating HRR and as a potential therapeutic strategy in killing KRAS‐mutant colorectal cancer cells." (PMID 28173629, 2017). "SLC25A22, which encodes the mitochondrial glutamate transporter, is overexpressed in colorectal cancer (CRC) and is essential for the proliferation of CRC cells harboring KRAS mutations." (PMID 29254168, 2017). "It has been reported that KRAS and BRAF mutations were negatively correlated with the response to targeting EGFR treatment in lung and colorectal cancers." (PMID 28556791, 2017). "Nevertheless, it is noteworthy that SIRT1 was specifically over-expressed in colorectal serrated lesions with KRAS or BRAF mutations, possibly contributing to their malignant transformation into colorectal cancer." (PMID 28977971, 2017). "In patients with colorectal cancer, mutant KRAS clones emerging during treatment with EGFR-specific antibodies declined during treatment breaks." (PMID 28716075, 2017). "Data on R0 resection rates in KRAS wild type colorectal cancer patients with liver-confined metastases were available in all RCTs (504 patients)." (PMID 28167959, 2017). "Data on progression-free survival in KRAS wild type colorectal cancer patients with liver-confined metastases were available in all RCTs (504 patients)." (PMID 28167959, 2017). "These favorable attributes prompted us to test the efficacy of Poloppin-II in an in vivo xenograft model using the mutant KRAS G13D-expressing colorectal cancer cell line, HCT116." (PMID 28807782, 2017).
colorectal cancer (continued). "Data on response rates in KRAS wild type colorectal cancer patients with liver-confined metastases were available in 3 RCTs (326 patients)." (PMID 28167959, 2017). "This supports miR-31-3p as a promising predictive biomarker for anti-EGFR therapy in KRAS WT advanced colorectal cancer." (PMID 29212194, 2017). "In summary, promising outcomes of vitamin C described in the management of KRAS and BRAF mutated colorectal cancer cells opened a new insight into treating aDTC." (PMID 28791253, 2017). "In this system, the expression levels of miR-193a-3p were modestly but significantly decreased in SW48 and DiFi, both KRAS/BRAF-wild-type colorectal cancer cells." (PMID 29115941, 2017). "In this study, we conducted an intensive process to select gene signatures and candidate compounds for KRAS-MT colorectal cancer using a novel approach to GECM." (PMID 27965461, 2017). "While inhibition of constitutive ERK1/2 signaling has limited effect in KRAS‐mutant colorectal cancer patients due to compensatory pathway activation, we found that combined inhibition of RAD51 and MEK1/2 significantly increases apoptosis by inducing DSBs." (PMID 28173629, 2017). "Here, the authors present BaseScope, a mutation-specific RNA in situ hybridization assay and spatially map colorectal cancer and adenoma KRAS, BRAF and PIK3CA driver gene mutant subclones." (PMID 29222441, 2017). "Mutant KRAS-expressing HCT116 colorectal carcinoma cells have previously been used to investigate resistance to PLK1 inhibition by the ATP-competitive PLK1 inhibitor, BI2536." (PMID 28807782, 2017). "Patients with obesity and patients with colorectal cancer of poor differentiation, lymph node metastasis, advanced TNM stage, MSI, KRAS, BRAF or PIK3CA mutations had shorter overall survival." (PMID 26515606, 2016). "In this pilot study interlesional mixed metabolic occurred in 43% of all patients with multiple evaluable tumour (KRAS wild-type) colorectal cancer lesions, treated with cetuximab monotherapy." (PMID 27196139, 2016). "We explored the association between the primary tumor site and cetuximab efficacy in KRAS wild-type colorectal cancer (CRC)." (PMID 27221731, 2016). "It has been reported recently that KRAS and BRAF mutations were negatively correlated with the response to targeting EGFR treatment in lung and colorectal cancers." (PMID 26909593, 2016). "Among the 374 colorectal cancer FFPE samples tested, the overall concordance between the IdyllaTM KRAS Mutation Assay and the confirmed reference routine test results was found to be 98.9%." (PMID 27685259, 2016). "We were interested in how genomic alterations, including alteration of the KRAS oncogene, in colorectal cancer influence cell proliferation under glucose-deprived conditions." (PMID 27924922, 2016). "An increased EGFR copy number is associated with a favorable response to anti-EGFR therapy in patients with KRAS wild-type colorectal cancer." (PMID 27014419, 2016). "The extension of markers from KRAS to RAS testing is the new paradigm for biomarker testing in colorectal cancer." (PMID 26573425, 2016). "For example, a clinical trial of cetuximab in colorectal cancer found that patients who expressed wild-type KRAS had increased progression-free survival with cetuximab compared to those with mutated KRAS." (PMID 27888810, 2016). "As breast cancers and colorectal cancers have similar BRAF and KRAS mutation spectra, it is logical that both cancers have a similar response to both cetuximab and panitumumab." (PMID 27655662, 2016). "We selected one hundred and twenty eight patients diagnosed with advanced colorectal cancer with a KRAS and NRAS unmutated tumor." (PMID 26824184, 2016). "In the colorectal cancer set, KRAS (42.5%), PIK3CA (17.8%) and KIT (10.9%) were the most frequently mutated genes." (PMID 26968814, 2016).
colorectal cancer (continued). "In colorectal cancer patients, LSC6 polymorphism in the let-7 binding site of the KRAS gene, has been proposed to predict the tumor responsiveness in EGFR-directed (cetuximab) treated patients." (PMID 26646588, 2016). "Responsiveness of older mlt heterozygotes (5 dpf) is restored by co-activation of oncogenic signaling pathways that are frequently activated in colorectal cancers (KRAS, Wnt)." (PMID 26893369, 2016). "Considering that a mutation of another oncogene BRAF plays a role in tumor aggressiveness of retractable colorectal cancer in down stream pathway of KRAS, a role of BRAF was studied." (PMID 27924922, 2016). "First, we determined KRAS status in a panel of 61 colorectal cancer samples using both methods to compare technical performance and concordance of results." (PMID 27485514, 2016). "There are several etiological pathways leading to colorectal cancer, the traditional biomarkers being microsatellite instability, the CpG island methylator phenotype, and somatic mutations in BRAF and KRAS." (PMID 27685259, 2016). "Though the efficacy of MEK inhibitors is being investigated in KRAS-mutant colorectal cancers (CRC), early clinical trials of MEK inhibitor monotherapy did not reveal significant antitumor activity." (PMID 27167191, 2016). "The amount of wild-type KRAS circulating in plasma was also significantly elevated in colorectal cancer patients in comparison to healthy controls (median, 7718.8 versus 481.25 copies/mL, respectively, p = 0.0002)." (PMID 27043547, 2016). "Wild-type KRAS was also significantly elevated in colorectal cancer patients compared to healthy controls (7718.8 versus 481.25 copies/mL, p = 0.0002)." (PMID 27043547, 2016). "It is true that the benefit of cetuximab or panitumumab, two well-known EGFR mAb approved by FDA, is restricted to patients with KRAS wild-type colorectal cancer, and only this subset of patients should receive these agents." (PMID 26840022, 2016). "The European Society for Medical Oncology and the American Society of Clinical Oncology have established major oncology guidelines that these antibodies be restricted to patients with KRAS wild-type colorectal cancers." (PMID 26812617, 2016). "In approximately 35.0%-42.0% of early colorectal cancer (CRC) pa­tients, KRAS mutations inhibit KRAS GTPase, resulting in constitutive activation of KRAS, and in turn, activation of the RAS/RAF signaling pathway." (PMID 26910894, 2016). "In conclusion, we demonstrate that miR-450b-5p induced by oncogenic KRAS is required for colorectal cancer progression." (PMID 27494869, 2016). "In this study, we investigated several aspects of the molecular epidemiology of KRAS and BRAF mutations in sporadic colorectal cancer precursor lesions." (PMID 26910894, 2016). "Efficacy of the combination of MEK and CDK4/6 inhibitors in vitro and in vivo in KRAS mutant colorectal cancer models." (PMID 27167191, 2016). "Other mutual exclusivities have been observed between HRAS and RHOA, in head and neck squamous cell carcinoma (HNSC) and between DIRAS2 and KRAS in colorectal cancer." (PMID 26860319, 2016). "Cetuximab has been approved for treatment of head and neck cancers by US FDA in 2004 and has been used to treat squamous carcinomas of the head and neck and colorectal cancers (CRCs) with wild-type KRAS." (PMID 27149458, 2016). "Results of APC and DCC LOH, KRAS and microsatellite instability indicate our colorectal cancer cases were typical of sporadic cancers following the ‘chromosomal instability’ pathway." (PMID 26970738, 2016). "It is now widely accepted that therapeutic antibodies targeting epidermal growth factor receptor (EGFR) can have efficacy in KRAS wild-type advanced colorectal cancer (CRC) patients." (PMID 27509063, 2016).
colorectal cancer (continued). "Oncogenic mutations of RAS (including NRAS and KRAS) and BRAF, which activate the MAPK signaling pathway, occur in 37 and 13 % of colorectal cancers, respectively." (PMID 26801617, 2016). "A similar requirement for activation of the IGF pathway has been demonstrated for KRAS-mutant colorectal cancer cells." (PMID 27437872, 2016). "We performed MAS-PCR assay analysis for KRAS on DNA isolated from 270 formalin-fixed paraffin-embedded (FFPE) colorectal cancer tissues." (PMID 26812617, 2016). "KRAS mutant colorectal cancer (CRC) patients develop lung and brain metastases more frequently than KRAS wild‐type (WT) counterpart." (PMID 26715198, 2016). "KRAS G12D is predominant in pancreatic ductal adenocarcinomas, non-small-cell lung cancer, colorectal cancer, and other carcinomas." (PMID 27127178, 2016). "In contrast to sporadic colorectal carcinomas, in which the majority harbors APC, CTNNB1 or KRAS mutations, colorectal carcinomas that arise in the setting of chronic inflammatory diseases have a very low frequency of these mutations." (PMID 26744320, 2016). "The ICER that we calculated is in line with previous findings for SCCHN, which has similarities in etiology and pathology, and for KRAS wild type colorectal carcinomas." (PMID 27100871, 2016). "The following example of utility illustrates such a probe-based assay to detect the most common KRAS mutation type (G12D), which accounts for ∼32.5% of all KRAS mutations, from FFPE samples of colorectal cancer patients." (PMID 25378315, 2015). "More specifically, a significantly larger number of KRAS-activating G > T DNA transversions were found at codon 12 of the KRAS gene in patients with NSCLC compared with those found in patients with colorectal cancer." (PMID 25962919, 2015). "Thirty-three patients ≤40 years with diagnosis of colorectal cancer and 41 patients with disease at >60 years of age were investigated for MSI, Mismatch Repair proteins expression, KRAS and BRAF mutations, hypermethylation, and LINE-1 hypomethylation." (PMID 26557847, 2015). "The BRAF, KRAS, and NRAS mutations are widely recognized to be the major causes of RAS/RAF/MEK/ERK pathway dysregulation in colorectal cancer." (PMID 26090613, 2015). "A more recent study in colorectal cancer described that MCT2 knockdown suppressed KRAS mutant colorectal tumour growth in vivo, indicating MCT2 as a promising target in colorectal cancer." (PMID 26035357, 2015). "In 2011 and 2013, researchers found that the contents of the exosomes released from these mutant KRAS colorectal cancer cells can influence normal cells in ways that would help a cancer to spread." (PMID 26132860, 2015). "MEK inhibitors, which have achieved significant success in the treatment of BRAF mutant melanoma, have been less effective as single agents in early clinical trials of both unselected and KRAS mutant colorectal cancer patients." (PMID 26136684, 2015). "SLFN11 expression predicts good better survival in colorectal cancer patients with KRAS exon 2 wild type who have received oxaliplatin based adjuvant chemotherapy." (PMID 26525741, 2015). "According to current clinical guidelines mutational analysis for KRAS and NRAS is recommended prior to EGFR-directed therapy of colorectal cancer (CRC) in the metastatic setting." (PMID 26220423, 2015). "Mutant KRAS colorectal cancer (CRC) cells release protein-laden exosomes that can alter the tumor microenvironment." (PMID 26132860, 2015). "In particular, both BRAF and KRAS mutations have been linked to CIMP status (high and low, respectively) in colorectal cancer." (PMID 25960768, 2015). "An oncogenic missense mutation p.V600E in BRAF, a downstream signalling molecule of KRAS, has been identified in around 5% of colorectal cancer tumors, though somewhat higher in this series at 10%, and results in activation of the MAPK signalling pathway." (PMID 25568935, 2015).